MSI1 (musashi RNA binding protein 1)
Diseases named in the same sentence as MSI1 in open-access papers (continued):
Sharing a sentence is not in itself a finding about the gene and the disease.
breast carcinoma (continued). "We first reconfirmed that MSI-1 knockdown downregulated breast cancer stem cell characteristics: Mammosphere formation was significantly repressed following MSI-1 knockdown, both in number and in size, confirming previous findings." (PMID 34291358, 2021). "Accordingly, our results demonstrated that the exogenous expression of miR-125b decreased not only the MSI1 protein but also expression of epithelial markers in breast cancer cells." (PMID 33541259, 2021). "It has demonstrated that MSI1 expression is increased in spheroid culture derived from breast cancer lines such as T-47D and MCF-7." (PMID 33541259, 2021). "In this study, we set out to understand the prognostic significance of MSI-1 expression in breast cancer and subsequently investigated ramifications of targeting MSI-1 for apoptosis and therapy resistance in hormone receptor-positive breast cancer cells." (PMID 34291358, 2021). "Given the decisive role of p21 in the regulation of breast cancer cell proliferation, we confirmed that colony formation was significantly downregulated after MSI-1 knockdown: clonogenic capacity was down by 25%." (PMID 34291358, 2021). "Msi1 function is also critical to the metastasis process in breast cancer and metastatic samples prevalently display high Msi1 expression." (PMID 33804958, 2021). "Contrary to the role of MSI1 in other tumors which increases cancer cell proliferation, in luminal tumors and luminal breast cancer cell lines, MSI1 is responsible for epithelial-luminal transition." (PMID 32448364, 2020). "Downregulation of MSI1 by RNAi changes the morphology of luminal breast cancer cells (MCF-7) to basal-like appearance." (PMID 32448364, 2020). "Reduction of MSI1 expression in breast cancer cell lines decreased the NOTCH1, c-MYC, ERBB2, and ERK1/2 expressions, which eventually inhibited the survival of tumor cells." (PMID 32448364, 2020). "It is reported that in spheroid breast cancer cell culture, expression of MSI1 elevates in CD133+ cancer stem cells." (PMID 32448364, 2020). "Methylation of CpG islands in the MSI1 promoter has been shown in several primary breast cancer tumors where hypomethylation leads to gene activation." (PMID 32448364, 2020). "Matching the pattern observed in primarytumors, we observed higher Msi1 and Msi2 expressionin luminal breast cancer lines than in basal lines." (PMID 25380226, 2014). "Msi1 was previously reported to inhibit Wnt pathway activation, as well as Notch activation through the negative regulator Numb in breast cancer and mammary epithelial cells." (PMID 23715514, 2013). "A549, but not H520 cells exhibited a marked upregulation of Numb following Msi1 KD, consistent with the suppression of Numb translation by Msi1 as previously observed in mammary epithelial and breast cancer cells." (PMID 23715514, 2013). "This has been suggested by lentivirus-mediated ‘knockdown’ (KD) of Msi1 in breast cancer and medulloblastoma cells, resulting in inhibition of proliferation and tumor xenograft growth." (PMID 23715514, 2013). "In the present study, Masi1 was functionally active in breast cancer cells, since inhibition of colony expansion and tumor growth by Msi1 KD resulted in increased Notch and reduced p21CIP1." (PMID 20727204, 2010). "Msi1 was expressed in 55% of the breast cancer cell lines and correlated with ErbB2 expression in 50% of the cell lines." (PMID 20727204, 2010). "Msi1 protein expression correlated with the 5-year survival events of breast cancer patients (P = 0.023)." (PMID 20727204, 2010). "Eleven of 20 human breast cancer cell lines (55%) expressed Msi1, and 13 cell lines showed a strong correlation between Msi1 and ErbB2 (P = 0.02)." (PMID 20727204, 2010). "Lentivirus RNA interference was used to reduce Msi1 expression in breast cancer cell lines MCF-7 and T47D grown as spheroid cultures and to assess stem cell gene expression and the growth of these cell lines as xenografts." (PMID 20727204, 2010).
breast carcinoma (continued). "Here we report that Msi1 is expressed in a high proportion of primary breast cancers and cell lines, particularly in metastatic disease." (PMID 20727204, 2010). "Msi1 expression was analyzed in 20 breast cancer cell lines and in 140 primary breast tumors by western blotting and immunohistochemistry, respectively." (PMID 20727204, 2010). "Our finding that 84% of breast cancer lymph node metastases expressed Msi1, in comparison to 42% of matched primary tumors, is consistent with the role of TICs in metastatic disease." (PMID 20727204, 2010). "In comparison with healthy tissues, MSI-1 was found to be upregulated in 40% of breast cancers." (PMID 37620963, 2023). "However, studies also demonstrated MSI-1 protein expression in testicular, spermatozoa, endometrial, ovarian and breast cancer tissue, suggesting that MSI-1 is actually present in more tissues than described in databases." (PMID 37620963, 2023). "In breast cancer cells, MSI1 promotes spheroid growth and colony formation, as well." (PMID 34062997, 2021). "In conclusion, MSI-1 is a prognostically relevant marker in breast cancer." (PMID 34291358, 2021). "In breast cancer, a positive correlation between expression of ErbB2 and MSI1 was observed." (PMID 33541259, 2021). "In contrast to MSI1's activity in other cancers where it promotes cancer cell proliferation, MSI1 is responsible for epithelial-luminal transition in luminal tumors and luminal breast cancer cell lines." (PMID 34587981, 2021). "MSI1 expression increases in CD133+ cancer stem cells in spheroid breast cancer cell cultures." (PMID 34587981, 2021). "Thus, the aim of our study was identification of putative miRNAs, which modulate MSI1 transcript in breast cancer cells." (PMID 33541259, 2021). "The documentation shows that MSI1 has an oncogenic function in breast cancer progression, therefore any modulation in MSI1 expression could be considered as a possible therapeutic approach against breast cancer progression." (PMID 33541259, 2021). "Another mechanism for MSI1 to promote cell growth in breast cancer is stabilizing the target mRNA." (PMID 32448364, 2020). "Therefore, considering the MSI1 role in breast cancer progression, this gene is essential for the preservation of epithelial-luminal transition." (PMID 32448364, 2020). "In breast cancer, increased Msi1 expression correlated with metastatic disease and poor survival." (PMID 23715514, 2013). "Future studies will address if Msi1 may serve as a TIC-selective therapeutic target for breast cancer and other malignancies." (PMID 20727204, 2010). "However, in breast cancer, MSI-1 may also downregulate the 26 S proteasome, another Notch pathway repressor, to sustain Notch signaling." (PMID 37620963, 2023). "It is unknown how Msi1 relates to other breast cancer markers, whether it denotes tumor initiating cells (TICs), and how it affects gene expression and tumor cell survival in breast cancer cells." (PMID 20727204, 2010). "The role of Msi1 in the etiology and progression of breast cancer is unknown." (PMID 20727204, 2010). "Thus, Msi1 expression is a prognosticator of TIC burden in breast cancer." (PMID 20727204, 2010). "The expression of MSI1 in HER2-positive breast cancer cell lines is correlated with HER2 and knock down of MSI1 reduces colony expansion of spheroid cultures in tumor cells." (PMID 33541259, 2021). "Musashi1 (MSI1) is an oncogenic protein with a crucial role in the proliferation and characteristics of the epithelial cells in breast cancer." (PMID 33541259, 2021). "Twenty human breast cancer cell lines and one immortalized human mammary epithelial cell line (MCF-10A) were used for western analysis of Msi1." (PMID 20727204, 2010). "MSI1 was a negative prognostic indicator of breast cancer patient survival, and was indicative of tumor cells with stem cell-like characteristics." (PMID 37968615, 2023).
breast carcinoma (continued). "Similarly, depletion of the stem cell marker Musashi-1 (MSI1) leads to the upregulation of CDKN1A/p21 and increased apoptosis in breast cancer cells." (PMID 38139316, 2023). "MSI-1 is a negative prognostic marker for disease-free and distant metastasis-free survival in breast cancer and tends to negatively influence overall survival." (PMID 34291358, 2021). "Surprisingly, in contrast to luciferase data, overexpression of miR-637 and miR-802 were not able to decrease the MSI1 expression in breast cancer cells." (PMID 33541259, 2021). "While the stem cell marker Musashi-1 (MSI-1) has been identified as a key player in a wide array of malignancies, few findings exist on its prognostic relevance and relevance for cancer cell death and therapy resistance in breast cancer." (PMID 34291358, 2021). "Nevertheless, an investigation about miRNAs’ role in regulation of MSI1 regarding inhibition of some cancers like breast cancer is lacking." (PMID 32448364, 2020). "In human breast cancer patients, MSI1 is a negative prognostic indicator of patient survival, and is indicative of tumor cells with stem cell-like characteristics." (PMID 22428049, 2012). "Msi1 is a negative prognostic indicator of breast cancer patient survival, and is indicative of tumor cells with stem cell-like characteristics." (PMID 20727204, 2010). "Neural stem and progenitor markers such as MSI1, DCX, NFL, HMGB1 were all significantly decreased after co-culture with breast cancer cells, suggesting that interaction with breast cancer cells leads to initiation of neural differentiation and maturation of NPCs." (PMID 39232464, 2024).
colon carcinoma (24 papers, 2010 to 2022). "Several studies proposed substantial regulation of MSI1 expression at the post–transcriptional level, in particular by miRNAs, including miR–125 or miR–137, both associated to tumor progression in colon cancer." (PMID 34062997, 2021). "In conclusion, our results show that miR-137 expression is decreased in colon cancer cell lines and rectal cancer tissues, and supports our overall hypothesis that loss of miR-137 promotes the overexpression of MSI1 in colorectal cancer." (PMID 25940441, 2015). "This evidence suggests that downregulation of the circ-0055625 gene inhibits colon carcinogenesis’ development and increases the sensitivity of colon cancer to IR by regulating MSI1." (PMID 36358938, 2022). "Studies have shown that knockout of circ-IFT80 in exosomes can reduce the radiosensitivity and apoptosis of colon cancer cells by regulating the miR-296-5p/MSI1 axis, promoting CRC cell proliferation and accelerating the cell cycle." (PMID 36142355, 2022). "MSI1 expression was significantly upregulated in colon cancer tissues and cells and increased in colon cancer cells following radiotherapy." (PMID 36358938, 2022). "In other kind of cancer, RBP Musashi1 (Msi1) promoted the proliferation of colon cancer cells by target the 3’UTR of p21(cip1)." (PMID 34863153, 2021). "Recent data showed that MSI1 was correlated with the progression of cervical cancer, lung cancer, oral squamous cell carcinoma, and colon cancer." (PMID 33882945, 2021). "In order to determine the properties of circ_0055625 and MSI1 in the progression and radiosensitivity of colon cancer, their expression was firstly detected in colon cancer tissues and cells." (PMID 33882945, 2021). "In this research, MSI1 expression was apparently upregulated in colon cancer tissues and cells and increased in colon cancer cells treated with radiation." (PMID 33882945, 2021). "These evidences indicated that circ_0055625 knockdown suppressed the development of colon cancer and improved sensitivity of colon cancer to IR by regulating MSI1." (PMID 33882945, 2021). "Circ_0055625 repression inhibited the progression and radioresistance of colon cancer by downregulating MSI1 through sponging miR-338-3p." (PMID 33882945, 2021). "Circ_0055625 and MSI1 were upregulated in colon cancer tissues and cells relative to control groups." (PMID 33882945, 2021). "Our finding provides a new mechanism for studying noncoding RNAs therapy of colon cancer and also implicates that circ_0055625 and MSI1 have potential to serve as biomarkers for colon cancer radiotherapy." (PMID 33882945, 2021). "In this study, we provided evidences that circ_0055625 mediated colon cancer development and sensitivity to IR by miR-338-3p/MSI1 pathway." (PMID 33882945, 2021). "Circ_0055625 knockdown or MSI1 silencing repressed cell proliferation, migration, and invasion and promoted cell apoptosis and radiosensitivity in colon cancer." (PMID 33882945, 2021). "In colon cancer–derived cells, MSI1 depletion suppressed the proliferation, colony formation, spheroid formation and progression of implanted colonspheres." (PMID 34062997, 2021). "Summary, the expression of circ_0055625 and MSI1 was increased in colon cancer tissues and cells, and radiation treatment increased circ_0055625 and MSI1 expression." (PMID 33882945, 2021). "Either circ_0055625 knockdown or MSI1 silencing hindered cell proliferation, migration, and invasion, whereas elevated cell apoptosis and radiosensitivity in colon cancer cells." (PMID 33882945, 2021). "Given the effects of both circ_0055625 and MSI1 on the progression and radiosensitivity of colon cancer, the relationship of circ_0055626 and MSI1 in mediating the progression and radioresistance of colon cancer was further explored." (PMID 33882945, 2021). "Radiation treatment apparently increased the expression of circ_0055625 and MSI1 in colon cancer cells." (PMID 33882945, 2021).
colon carcinoma (continued). "Downregulation of MSI1 increases apoptosis and G2/M arrest in human colon carcinoma HCT 116 cell line and leads to regression of tumor xenografts." (PMID 32448364, 2020). "It was shown that MSI1 is an activator of Wnt and Notch pathways controlled by miR-133a, miR-138, miR-342, miR-491, and miR-541 in colon carcinoma cell lines." (PMID 32448364, 2020). "In colon cancer, MSI-1 expression and epithelial growth factor pathway activity were correlated, the latter being another key regulator of radioresistance that is specifically targeted in radiation-centered clinical trials." (PMID 32245259, 2020). "We validated Gn binding to MSI1 using surface plasmon resonance, nuclear magnetic resonance, and cellular thermal shift assay, and tested the effects of Gn on colon cancer cells and colon cancer DLD-1 xenografts in nude mice." (PMID 30097032, 2018). "A previous study among colon cancer patients has shown that overexpression of MSI1 in colon cancer lesions, compared to paired normal colonic mucosa, was associated with poorer metastasis-free survival and poorer overall survival." (PMID 28542447, 2017). "In colon cancer forced expression of Notch3 increased the level of MUSASHI-1 (MSI-1), whereas silencing of Notch3 by shRNA reduced the MSI-1 level in both colorectal cancer cells and tumor xenografts." (PMID 29104587, 2017). "In summary, miR-137 inhibits clonogenic growth, supporting its predicted role as a tumor suppressor miRNA that reduces colon cancer stem cell properties, in part by directly down-regulating MSI1." (PMID 25940441, 2015). "Knocking down MSI1 in human colon cancer cell lines reduces growth, enhances apoptosis after radiation treatment and reduces colon cancer proliferation, migration and invasion in vitro." (PMID 25940441, 2015). "Since MSI1 is a regulator of intestinal multipotent stem cells, we predicted that miR-137 reduces clonogenic cell growth in colon cancer." (PMID 25940441, 2015). "Multiple studies have found an overexpression of MSI1 in a broad range of cancer types, including breast, lung and colon cancer." (PMID 25940441, 2015). "MSI1 mRNA and protein is over-expressed in a panel of colon cancer cell lines compared to normal colon epithelial cell line, CCD-841." (PMID 25940441, 2015). "miR-137 restoration in colon cancer cell lines, reduces MSI1 mRNA and protein levels, and inhibits cell growth, colony formation and tumorsphere growth." (PMID 25940441, 2015). "In summary, miR-137 restoration in colon cancer cell lines significantly reduced Wnt and Notch signaling; two important oncogenic signaling pathways regulated by MSI1 and involved in colorectal cancer progression." (PMID 25940441, 2015). "Several studies have shown that Msi1 also promotes cell growth and tumor formation in colon cancer and lung cancer." (PMID 25362645, 2014). "Accordingly, in our previous transcriptomic analysis of DMH-induced colon tumours, Msi-1 was actually downregulated compared to normal mucosa." (PMID 23374535, 2013). "Other groups have shown that MSI1 up-regulates the Notch signaling activity in medulloblastoma, colon cancer, mammary progenitor cells, and endometrial carcinoma." (PMID 22428049, 2012). "MSI1 has been shown to have a role in the development of colon cancer." (PMID 36358938, 2022). "Further studies showed that circ-0055625 can act as a sponge for miR-338-3p, and knockout of circ-0055625 can block cell proliferation, migration, and invasion by regulating the miR-338-3p/MSI1 axis, and improve colon cancer cell proliferation, apoptosis, and radiosensitivity." (PMID 36142355, 2022). "Furthermore, Kaplan-Meier methods demonstrated that both high circ_0055625 and MSI1 expression were correlated with poor survival rate of colon cancer patients." (PMID 33882945, 2021). "In addition, results also showed that MSI1 repression restrained cell proliferation, migration, and invasion, whereas improved cell apoptosis in colon cancer." (PMID 33882945, 2021).